LINC02555 (long independently transcribed non-coding RNA 2555)
Synonyms: AC079630.2
Gene: Long non-coding RNA gene on chromosome 12 (40,140,926 to 40,158,600, reverse strand). Ensembl gene ENSG00000260943.
Diseases named in the same sentence as LINC02555 in open-access papers:
LINC02555 is named in the same sentence as 3 diseases in open-access papers, as found by Europe PMC text mining. Sharing a sentence is not in itself a finding about the gene and the disease. The quoted sentences say what the papers report.
adenoma (1 paper, 2021). A neoplasm arising from the epithelium. "The expression of LINC02555 and LINC02471 increased during the progression from adenoma to carcinomas and was significantly higher in fvPTC and clPTC than in FA." (PMID 34408227, 2021).
tumor (1 paper, 2022). "However, the expression level of LINC02555 and PTCSC3 were higher in normal lung tissues, reflecting they may serve as repressive roles in tumor growth or progression." (PMID 35372012, 2022).
LINC02555 also shares sentences with these, for which no sentence is quoted: carcinoma (1 paper).